CD22 (CD22 molecule)
Diseases named in the same sentence as CD22 in open-access papers (continued):
Sharing a sentence is not in itself a finding about the gene and the disease.
infection (19 papers, 2018 to 2026). The state of being infected such as from the introduction of a foreign agent such as serum, vaccine, antigenic substance or organism. "The survival rate of the CD22-/- group was much lower than the control group (p<0.001), with 100% of the CD22-deficient mice reaching the experimental endpoint by 72h post-infection, whereas 56% of the control mice survived to the end of the experiment, at 168h." (PMID 32324805, 2020). "On-CD22 transcripts were highly expressed in the head kidney and peripheral blood of healthy fish and showed significant expression changes following infection with Streptococcus agalactiae, Aeromonas hydrophila, or stimulation with poly(I:C)." (PMID 41594875, 2026). "Among the signals from LZ GC B cells to DCs, multiple MHC II protein complex subunits exhibited enhanced interaction with Cd4, while signals including Fcer2a-(Itgax+Itgb2) and Cd22-Ptprc were weakened by PCV2 infection." (PMID 41011514, 2025). "Genes uniquely triggered by M. riyadhense infection compared with other mycobacteria included Cd22, Gpr65, Adh7 and TrnT; however, no functional categories were statistically enriched from this category of genes." (PMID 34396095, 2021). "Other risk factors for infection after CAR T cell therapy shown by previous studies included higher number of prior treatments, higher doses of CAR T cells, older age, previous history of infection, and CD22-specific CAR T cells." (PMID 32759935, 2020). "In contrast, B2 and B1a cell numbers were unchanged in the spleen of both strains after infection, with the exception of lower B2 cells in CD22-/- mice at 48 hours." (PMID 32324805, 2020). "Next, the progress of pneumococcal disease in CD22-/- mice and controls was investigated in an experiment that determined pneumococcal numbers in the lung, blood and spleen at over 48 hours post-infection." (PMID 32324805, 2020). "Among the signals from macrophages to LZ GC B cells and memory B cells, the Lgals9-Ighm/Cd45 signaling showed a greater enhancement by PCV2 infection, while those signals that were originally stronger in the control group, such as Ptprc-Cd22, Cd52-Siglecg, and App-Cd74, were weaker." (PMID 41011514, 2025). "The upregulation of genes encoding B cell surface molecules—including CD19, MS4A1, CD22, FCER2, and CR1—may be involved in the proliferation and differentiation of memory B cells induced by the vaccine doses, following BA.5 infection." (PMID 39499071, 2024). "However, numbers of conventional B cells, as well as B1a cells were highly elevated in the lungs of C57BL/6 mice at each time point following infection, but much less so in CD22-/- mice." (PMID 32324805, 2020). "CD22-deficiency not only leads to increased susceptibility to WNV, but also accelerates murine AIDS MAIDS induced by a murine leukemia virus, CD22−/− mice had a more rapid onset of splenomegaly and lymphadenopathy 4 weeks after infection." (PMID 30323814, 2018). "Also, NeuAc O-acetylation influences the binding to viral neuraminidases during infection, and may have immunoregulatory effects by affecting the affinity of the sialylated glycan for lectins (e.g., CD22) or bacterial sialidases." (PMID 40821702, 2025). "Expression of CD22 on DN3 cells from severe SARS-CoV-2 infection trends to a higher level of expression than DN3 cells from heathy controls and subjects with mild infection." (PMID 36131937, 2022). "We found lower IgM levels in the BAL of CD22-/- mice compared to the C57BL/6 control at early time points (3 hours and 6 hours) (p<0.01) after infection." (PMID 32324805, 2020). "On the other hand, 24 genes were significantly upregulated by infection in the R line of the HSF flock, such as CD19, CD22, CD79B, two complement-related genes CFI and CR2 (complement C3d receptor 2), FGG, and FGA (fibrinogen alpha chain)." (PMID 30678719, 2019).
infection (continued). "Also, lower GM-CSF levels were detected 3 hours after infection in the BAL of CD22-/- mice compared to the control (p<0.05), whereas IgM and GM-CSF concentrations in the blood were similar in CD22+/+ and CD22-/- mice." (PMID 32324805, 2020). "It is worth noting that we found that B cell markers (i.e., IgT, IgM, CD22) but not T cells markers are significantly upregulated after infection with Ich." (PMID 31499339, 2019). "Together, these data indicate that while CD72 expression is depressed with severe SARS-CoV-2 infection, the expression of the CD22 and FCRL5 inhibitory receptors on DN2 cells does not change with severe infection." (PMID 36131937, 2022). "Thus, unlike CD19 and CD22 CAR therapy, which primarily affects B cells, 5CAR and 7CAR therapies result in broad dysregulation across multiple immune cell types, providing a basis for infection prevention and safer CAR-T therapy." (PMID 41290542, 2025).
blood cancer (3 papers, 2017 to 2023). "Moxetumomab pasudotox-tdfk (Lumoxiti®) against CD22, approved for blood cancer in 2018, was internalized through clathrin-coated pits into the endocytic compartment." (PMID 36546903, 2022). "Inotuzumab ozogamicin (Besponsa®) against CD22 with an acid-cleavable linker, approved for blood cancer in 2017, was internalized into cells and released a potent cytotoxic agent, N-acetyl-γ-calicheamicin, to the cytoplasm and the nucleus after lysosomal escape." (PMID 36546903, 2022). "However, other blood tumor clinical CAR-T target genes, CD22 and TNFRSF17, are not essential in any cell line of their respective indications." (PMID 37835579, 2023).
bacterial infection (2 papers, 2020 to 2022). "After bacterial infections, CD22-deficient mice had strongly reduced B cell populations in the lung, including GM-CSF producing, IgM secreting innate response activator B cells, which are crucial for protection." (PMID 32324805, 2020). "Furthermore, long-term engraftment of CAR T cells may be associated with different adverse events including the B-cell aplasia and bacterial infection usually observed in CD19 and CD22 autologous CAR T-cell therapies." (PMID 35773273, 2022).
immune disorders (2 papers, 2018 to 2024). "In summary, this study elucidates the immunopathology of refractory seronegative MG, highlighting immune disorders centered on B cells and diminished soluble CD22 levels." (PMID 38711503, 2024). "DEGs that enriched to “immune system diseases” played critical roles in cell-matrix communication (THY1, LVRN, LUM, TIMP3, SPOCK1, LGALS3BP, FAT2, and SERPINE2) as well as inflammation (IL1R2, CD22, PTGES, TNFSF10, IL2RB, C3, SERPING1, and IL-17RE)." (PMID 30131724, 2018).
neurodegenerative disease (2 papers, 2019 to 2023). A disorder of the central nervous system characterized by gradual and progressive loss of neural tissue and neurologic function. "In particular, mounting evidence from AD patients and experimental models indicates pivotal roles for TREM2, CD33, and CD22 in neurodegenerative disease progression." (PMID 37276426, 2023). "Above all, aged microglia specifically expressing CD22 in CNS could be a potential and viable molecular target in neurodegenerative diseases, especially for AD and POCD." (PMID 31244847, 2019). "While increasing evidence indicates that ITAM/ITIM-containing immune receptors (i.e., TREM2, CD33, and CD22) are critically involved in AD progression, we still lack in-depth knowledge of the intracellular signaling molecules employed by these immune receptors to influence neurodegenerative disease." (PMID 37276426, 2023). "The CD22 blockade appears to be more promising than PD-1/PD-L1 blockade, and may exhibit better efficiency and lesser side effects as a therapeutic strategy in neurodegenerative diseases." (PMID 31244847, 2019).
inflammation (1 paper, 2017). Aberrant reaction of the microcirculation characterized by movement of fluid and leukocytes from the blood into extravascular tissues. "When 1,3-β-glucan-induced lung inflammation developed into the late stage, anti-CD22 treatment significantly limited the increase of IL-10 compared with that in glucan group." (PMID 28428789, 2017).
CD22 also shares sentences with these, for which no sentence is quoted: follicular lymphoma (8 papers); ovarian carcinoma (5); Breast tumor (3); gastric cancer (3); Hodgkins lymphoma (3); Thrombocytopenia (3); acute T-cell leukemia (2); anaplastic large cell lymphoma (2); anemia (2); brain tumor (2); hepatocellular carcinoma (2); myelodysplastic syndrome (2); myeloid neoplasm (2); neuroblastoma (2); Neurologic Disease (2); pancreatic cancer (2); Parkinson disease (2); T-cell lymphoma (2); triple-negative breast carcinoma (2); acute graft versus host disease (1); AIDS (1); Allergy (1); bladder cancer (1); bladder urothelial carcinoma (1); capillary leak syndrome (1); cervical cancer (1); childhood cancer (1); cholangiocarcinoma (1); colon adenocarcinoma (1); colorectal tumors (1).
A further 45 diseases each share a sentence with CD22 in 1 paper.